PCA3 (prostate cancer associated 3)
Diseases named in the same sentence as PCA3 in open-access papers (continued):
Sharing a sentence is not in itself a finding about the gene and the disease.
prostate carcinoma (continued). "For instance, a urine-based molecular assay that identifies the presence of the Prostate Cancer Antigen 3 (PCA3) lncRNA molecule is commonly used for prostate cancer diagnosis." (PMID 39061232, 2024). "Some lncRNAs have already found application as diagnostic biomarkers; one notable example is PCA3, which is employed in the PROGENSA PCA3 urine test for prostate cancer diagnosis ﻿." (PMID 38095719, 2024). "Several urinary biomarkers were reported as PCa biomarkers, including Engrailed 2 protein, sarcosine, alpha-methyl CoA-racemase (AMACR), and the prostate cancer gene 3 (PCA3), a long noncoding RNA (lncRNA) exclusively produced in prostate cancer tissues." (PMID 38793175, 2024). "In the present study, we have explored the application of PCA3 biomarkers for on-chip electrochemical sensor development, reducing the detection time and enhancing the sensitivity for prostate cancer detection in a cost-effective setting." (PMID 39589993, 2024). "Because elevated PSA levels can be due to several factors other than prostate cancer, PCA3 would offer more specificity when determining the presence of a tumor in the prostate." (PMID 38173042, 2024). "mRNA PCA3 plays an essential role in prostate cancer cell survival by modulating androgen receptor signaling." (PMID 38254807, 2024). "A good example is the lncRNA PCA3, whose increased expression signals a prostate cancer and can be detected in urine, together with enhanced MALAT1 and LincRNA-p21." (PMID 38790894, 2024). "Long non-coding RNAs, including PCGEM, PCAT-1, MALAT, and the prostate cancer gene 3 (PCA3), have recently been discovered to be deregulated in PC, describing the PCA3 gene’s extreme over expression in prostatic cancers." (PMID 38723038, 2024). "For instance, in prostate cancer, Prostate cancer antigen 3 (PCA3), a lncRNA, can form a double-stranded RNA with PRUNE2 (a human homolog of the Drosophila prune gene) to attract ADAR1 binding and exert an editing effect to regulate PRUNE2’s level." (PMID 38233935, 2024). "Even small amounts of PCA3 can indicate a significant likelihood that a patient either has or will develop prostate cancer." (PMID 37754118, 2023). "Currently, PCA3 is also an auxiliary biomarker in prostate cancer; its use was approved by the Food and Drug Administration (FDA) in 2012 due to its clinical utility by reducing the number of unnecessary biopsies in patients." (PMID 37108589, 2023). "For example, PCA3 (prostate cancer antigen 3, lncRNA) is considered a biomarker in prostate cancer, and the high expression of lncRNAs CCAT2, MALAT1, and NEAT1 is related to worse OS in breast cancer." (PMID 36924407, 2023). "Recently, a biosensor that detects prostate cancer via PCA3 biomarkers has been developed via electrochemical and impedance methods." (PMID 36986729, 2023). "Some of them such as PCA3 are highly specific for this kind of cancer, representing an appropriate biomarker for prostate cancer." (PMID 37025585, 2023). "For example, in human prostate cancer, the antisense intronic lncRNA PCA3 inactivates the tumor-suppressor gene PRUNE2 at the RNA level through an ADAR-mediated mechanism and promotes malignant cell growth." (PMID 36795564, 2023). "PSA, PSMA, PB and PCA3/DD3 promoters have been used in adenovirus-mediated gene therapy of prostate cancer." (PMID 37056394, 2023). "The MiPS assay tests for the presence of two prostate cancer biomarkers in post-DRE urine specimens: PCA3 gene mRNAs, found to be overactive in 95% of all PCa-s, and TMPRSS2: ERG mRNAs, which is also a strong indicator of PCa." (PMID 38201592, 2023). "On the basis of these data, the use of PCA3 in the repeat biopsy setting would reduce the number of biopsies by almost half, and only 3% of men with a low PCA3 score would have high-grade prostate cancer that would be missed." (PMID 36768533, 2023).
prostate carcinoma (continued). "One of the most established lncRNA, PCA3, has been approved for use in the diagnosis of prostate cancer and is currently being explored as a therapeutic target." (PMID 37686283, 2023). "Given its specificity for tumour tissue compared to healthy one and that its undetectability in other tissues, PCA3 is the most specific gene for prostate cancer known so far." (PMID 37143733, 2023). "Salameh found that ADAR1-mediated editing of prostate cancer antigen 3 (PCA3) increased its stability and expression in prostate cancer (PC), further promoting tumorigenesis." (PMID 36895481, 2023). "An electrochemical method of prostate cancer-specific DNA sequences (PCA3) using chondroitin sulfate-AuNPs has been demonstrated to treat prostate cancer." (PMID 36615558, 2023). "For example, PCA3 is abnormally highly expressed in prostate cancer cells, and it is related to the Gleason pathological grading of prostate cancer, which is a promising prognostic marker." (PMID 36643625, 2023). "The most important milestone in the field of lncRNA research is probably approval of urinary PCA3 as a biomarker for detection of prostate cancer by the United States Food and Drug Administration." (PMID 37025585, 2023). "Prostate cancer antigen 3 (PCA3) has been approved by the FDA for use as a prostate cancer screening test." (PMID 36982952, 2023). "In light of this, the structure is used for the accurate detection of the prostate cancer marker urine prostate cancer antigen 3 (PCA3), exhibiting high sensitivity and selectivity." (PMID 37298846, 2023). "For example, the T2:ERG and urine PCA3 in a large cohort of prostate cancer patients to evaluate their utility as a novel cancer biomarker panel." (PMID 36765916, 2023). "Commercially available PROGENSATM, prostate cancer biomarker quantifies PCA3 expression ratio normalized as input control for prostate specific antigen (PSA) mRNA." (PMID 36092905, 2022). "According to the NCCN Guidelines Updates of 2018, PCA3 >35 can be used as a biomarker for early detection of prostate cancer." (PMID 35289508, 2022). "PCA3, a lncRNA regulated by a steroid receptor is overexpressed in most prostate cancer patients and is detected in the urine of these cancer patients." (PMID 35281858, 2022). "For instance, a lncRNA called prostate cancer antigen 3 (PCA3) has been applied in clinical practice as a biomarker for prostate cancer diagnosis." (PMID 35030964, 2022). "In contrast, another two prostate-specific lncRNAs (PCGEM1 and PCA3) are overexpressed in prostate cancer and promote the cell proliferation ability and inhibit the cell apoptosis ability of prostate cancer cells." (PMID 36289466, 2022). "This study evaluated the potential of PCA3 as a diagnostic biomarker and compared the performance characteristics of urine PCA3 and serum PSA as diagnostic tools for prostate carcinomas in Ghanaian men." (PMID 36246565, 2022). "LncRNA PCA3 is an lncRNA that is currently well studied in prostate cancer, is significantly higher expressed in prostate cancer tissues, and can be detected in urine as an early molecular diagnostic marker." (PMID 35310927, 2022). "UCA1 is an lncRNA similar to PCA3, and the mechanism of promoting the occurrence and development of prostate cancer has been widely explored." (PMID 35289508, 2022). "PCA3 is a prostate-specific marker often overexpressed in prostate cancer and can be detected easily through non-invasive urine collection." (PMID 36649030, 2022). "With respect to prostate cancer, there are also related reports, for example, PCA3 and SChLAP1 were reported to be biomarkers for prostate cancer." (PMID 35310913, 2022). "For example, urine PCA3 (lncRNA PCA3) has been authorized by the FDA as a urine marker for prostate cancer due to its high sensitivity and specificity over PSA (prostate-specific antigen)." (PMID 35864503, 2022).
prostate carcinoma (continued). "PCA3 is significantly elevated in patients with prostate cancer, and several available studies show the utility of PCA3, as a urinary biomarker, for the diagnosis of early prostate cancer with reasonable specificity and sensitivity." (PMID 35627227, 2022). "Patients with prostate cancer were found to have increased expression of the lncRNA PCA3 in sEVs obtained from their urine; therefore, PCA3 in urine-derived sEVs can be used as a marker for the early diagnosis of PCa." (PMID 36612097, 2022). "In 95% of prostate cancer patients, higher expression of PCA3 and ncRNA have extensively been reported in blood samples." (PMID 36092905, 2022). "For example, lncRNA PCA3, which is highly upregulated and specific to prostate cancer, was detected in the urine with levels that correspond to the severity of prostate cancer." (PMID 35913967, 2022). "The first lncRNA to be validated as a biomarker and used in clinical practice was PCA3 for the diagnosis of prostate cancer." (PMID 36010859, 2022). "Prostate cancer antigen 3 (PCA3) was the first lncRNA identified in 1999 mapped on chromosome 9q21–22 and found to be overexpressed in greater than 95% of prostate cancers." (PMID 34071230, 2021). "MiPS is a urine test for detecting two prostate cancer biomarkers: a piece of RNA made from the prostate cancer antigen 3 (PCA3), and another RNA marker that is found only when TMPRSS2 and ERG abnormally fuse (T2:ERG)." (PMID 34884946, 2021). "Among them, PCA3 (Prostate Cancer Antigen 3) is the most well-recognized lncRNA which can be used for the diagnosis of prostate cancer and is approved by FDA." (PMID 34439315, 2021). "For example, lncRNA PCA3, released in the urine of prostate cancer patients, has been a sensitive and more specific marker for these patients than serum prostate-specific antigen testing, and it is also a convenient and less invasive procedure." (PMID 34885213, 2021). "CV and DPV measurements proved the concept of electrochemical detection of the prostate cancer marker PCA3 using aptamers labeled with methylene blue." (PMID 34884504, 2021). "Some lncRNAs are already being used as biomarkers in the clinic such as the lncRNA Prostate cancer antigen 3 (PCA3) approved by the FDA as a prostate cancer biomarker, with a sensitivity of 58–82% and a 56–76% specificity." (PMID 34439196, 2021). "Intriguingly, lncRNA PCA3 is much more specific and sensitive than prostate-specific antigen, the conventional gold standard for prostate cancer." (PMID 34527584, 2021). "Notable urinary biomarkers include prostate cancer antigen 3 (PCA3), which is a noncoding messenger RNA (mRNA) overexpressed in prostate cancer tissue and detectable in urine after a digital rectal examination (DRE)." (PMID 34026653, 2021). "The authors calculated this change in resonance frequency and detected PCA3 RNA, a nucleic acid prostate cancer marker." (PMID 34947679, 2021). "It was evidenced that LncRNA prostate cancer antigen 3 (PCA3) is overexpressed in 95% of prostate cancers and can be used as molecular markers in prostate cancers, which was approved by the US food and drug administration in 2012." (PMID 34303380, 2021). "LncRNAs PCA3 (prostate cancer antigen 3) is proved to contribute to prostate cancer development by promoting the proliferation and metastasis of cancer cells." (PMID 34319909, 2021). "PCA3 noncoding RNA is involved in the control of prostate cancer cell survival, in part through modulating androgen receptor signaling." (PMID 33490732, 2021). "Hessels and colleagues report an overexpression of PCA3 in urine obtained from patients with prostate cancer, thereby leading to the development of non-invasive PCA3 urine tests for clinical detection of early prostate cancer." (PMID 33803619, 2021). "For example, the lncRNA PCA3 is elevated in patients with prostate cancer and due to its stability in biological fluids, PCA3 can be easily detected in urine." (PMID 34575473, 2021).
prostate carcinoma (continued). "At present, cheRNA PCA3 has been used in the clinical diagnosis of prostate cancer for its high expression, providing a reliable basis for the treatment of prostate cancer." (PMID 33937246, 2021). "Although PCA3 was discovered a long time ago, until now, its use in prostate cancer diagnosis has been limited to the Progensa PCA assay, licensed in the USA in 2012." (PMID 34884504, 2021). "PCA3 is a prostate-specific lncRNA that is highly overexpressed in most types of prostate cancer cells and is indicated for detecting the presence of malignancy in men undergoing repeat prostate biopsy." (PMID 33800703, 2021). "LncRNAs HULC and PCA-3 have been measured to be significantly upregulated in liver and prostate cancers, respectively." (PMID 32607061, 2020). "PCA3 is a long non-coding RNA originally detected in urine sediments following prostatic massage and is a recognized upregulated marker of prostate cancer." (PMID 33172003, 2020). "As expected, KLK3 Ct values strongly correlated with Ct values of other genes which have been reported to play a role in prostate cancer (i.e., PCA3, AMACR, TRPM8, MSMB and PSGR)." (PMID 32630458, 2020). "Currently, the most well-recognized lncRNA is PCA3, which has been approved for use in the diagnosis of prostate cancer." (PMID 33330574, 2020). "Of note, PCA3 expression is detectable at high level in the urine of prostate cancer (PCa) patients." (PMID 32398974, 2020). "One lincRNA PCA3-based test (the PROGENSA PCA3 assay approved by the FDA) has been used as a marker for the detection of prostate cancers (Evaluation of Genomic Applications in Practice and Prevention [EGAPP] Working Group, 2014)." (PMID 32523949, 2020). "LncRNA PCA3 was even employed as a prostate cancer marker in a liquid biopsy test, though the test specificity remains debated." (PMID 33329688, 2020). "The diagnostic value and suitability of prostate cancer antigen 3 (PCA3) for the detection of prostate cancer (PCa) have been inconsistent in previous studies." (PMID 31961625, 2020). "Prostate cancer antigen 3 (PCA3) is a gene that codes for a mRNA that is overexpressed in prostate cancer tissue." (PMID 32957584, 2020). "For example, a prostate-specific lncRNA PCA3 in urine has been identified as the most specific biomarker for detection of prostate cancer with higher specificity than the widely-used prostate- specific antigen test." (PMID 32686826, 2020). "Univariate logistic regression revealed that, independently, Vn96-isolated EV PCA3 value was a modest but significant predictor of prostate cancer classification (OR = 1.0960, 95% CI = 1.0298–1.1665, p value = 0.0039)." (PMID 33172003, 2020). "Of note, the addition of Vn96-isolated EV PCA3 values to our seven mRNA/2 miRNA model improved the accuracy of prostate cancer diagnosis to an AUC of 0.9." (PMID 33172003, 2020). "PCA3 levels in urine show higher sensitivity in prostate cancer diagnosis than the standard PSA tests." (PMID 33231563, 2020). "Urine exosome derived PCA3 and TMPRSS2-ERG have been found to associated with prostate cancer diagnosis and prostate cancer risk stratification." (PMID 31013716, 2019). "The detection of PCA3 in urine is a more specific marker for prostate cancer diagnosis than the commonly used factor, prostate specific antigen (PSA), and has been widely applied in the clinic." (PMID 31456817, 2019). "The Progensa PCA3 assay (Progensa Test Kit, Hologic, Marlborough, MA, USA) is an FDA-approved prostate cancer diagnostic test for use in men aged 50 years or older with elevated serum PSA and previous negative biopsy results." (PMID 31013716, 2019). "The most prominent example of such a biomarker is prostate cancer antigen 3 (PCA3), a lncRNA expressed at high levels in prostate cancer." (PMID 31456817, 2019). "For instance, the PCA3 (also called DD3) and PCGEM1 were the first lncRNAs that were associated with cancer because they were overexpressed in prostate cancer." (PMID 31448238, 2019).
prostate carcinoma (continued). "For example, PCA3 was a potential prognostic marker of prostate cancer, which was more sensitive than the most widely used biomarker, prostate specific antigen (PSA)." (PMID 30873207, 2019). "The prostate cancer related lncRNA PCA3 is silent in most cancer patients, and is highly expressed in 96% of prostate cancers." (PMID 31877126, 2019). "The PSA, 4Kscore, phi, SelectMDx, PCA3, and Confirm MDx assays provide information on suspected prostate cancer patients who need to undergo initial biopsy." (PMID 31013716, 2019). "Based on several studies on large patient cohorts, urine PCA3 is found to be a superior serum PSA for prostate cancer diagnosis." (PMID 31013716, 2019). "For example, the lncRNA PCA3 (prostate cancer antigen 3) is an FDA-approved biomarker for prostate cancer prediction." (PMID 31266446, 2019). "The first reported lncRNA with an aberrant expression in cancer was prostate cancer associated 3 (PCA3), which was identified via differential display analysis of transcripts in normal human prostate cancer." (PMID 31001323, 2019). "The Food and Drug Administration (FDA) approved PCA3 as more specific and urine biomarker lncRNA for prostate cancer." (PMID 31141943, 2019). "PCA3 is prostate-specific and has been shown highly expressed in prostate cancer, and has been identified as a genetic marker for prostate cancer diagnosis." (PMID 30367578, 2018). "This has led to the commercialization of a PCA3 assay to permit rapid detection of PCA3 in prostate cancer (Gen-Probe Incorporated, Progensa PCA3 Assay)." (PMID 29732012, 2018). "One example is lncRNA prostate cancer antigen 3 (PCA3), which is upregulated in human prostate cancer." (PMID 30585209, 2018). "The PCA3 level was increased approximately 100-fold in prostate cancer tissue compared to paired normal prostate tissues." (PMID 30200254, 2018). "One of the famous lncRNA in prostate cancer is prostate cancer antigen 3 (PCA3), the expression of which significantly increased in prostate tumors compared with expression in adjacent non-neoplastic prostate tissue." (PMID 29412547, 2018). "The group evaluated 1244 men and showed that combination of TMPRSS2:ERG plus PCA3 is superior in diagnosing prostate cancer having AUC of 0.751 compared to PSA plus PCA3 (AUC: 0.726) and PSA alone (AUC: 0.585)." (PMID 30200254, 2018). "A promising biomarker for PCa diagnosis is prostate cancer gene 3 (PCA3) which is highly over-expressed by prostatic cancer cells." (PMID 28061466, 2017). "The use of lncRNAs as molecular biomarkers emerged with the characterization of the long noncoding RNA PCA3 (prostate cancer antigen 3) and the finding of its upregulated expression in prostate cancer patients." (PMID 28703782, 2017). "PCA3 has been recently approved as a urine biomarker for prostate cancer by the US Food and Drug Administration." (PMID 28634418, 2017). "In prostate cancer patients, the presence of two well-known biomarkers in exosomes recovered from urine samples, such as the PCA-3 and TMPRSS2:ERG mRNAs, indicated an alternative strategy for early screening of the disease." (PMID 28098821, 2017). "The US Food and Drug Administration has approved PCA3 RNA-based urine test for the diagnosis of prostate cancer." (PMID 28912732, 2017). "The up-regulation of lncRNA PCA3 (DD3) has proven to be a reliable biomarker for prostate cancer early detection." (PMID 28346506, 2017). "A meta-analysis of several studies has determined the validity of PCA3 levels in urine samples for prostate cancer diagnosis, with a summary sensitivity of 62% and specificity of 75%." (PMID 28634418, 2017). "In prostate cancer, several miRNAs (such as miR-21 and miR-107) and mRNA (AGR2 splice variant, PCA3, and TMPRSS-ERG) have been reported to be biomarkers in urinary EVs11." (PMID 28211531, 2017).